NADK2 (NAD kinase 2, mitochondrial)
Description:
Mitochondrial NAD(+) kinase that phosphorylates NAD(+) to yield NADP(+). Can use both ATP or inorganic polyphosphate as the phosphoryl donor. Also has weak NADH kinase activity in vitro; however NADH kinase activity is much weaker than the NAD(+) kinase activity and may not be relevant in vivo.
Synonyms: C5orf33; MNADK; NADKD1; FLJ30596; DECRD
Tractability: Small molecule: a structure with a bound ligand is known. PROTAC: ubiquitination databases record sites on it; its protein half-life has been measured.
Gene: Protein-coding gene on chromosome 5 (36,192,589 to 36,242,279, reverse strand). Ensembl gene ENSG00000152620.
Subcellular location: Mitochondrion
Subcellular location (Human Protein Atlas): Mitochondria
Pathways (Reactome):
Metabolism: Nicotinate metabolism
Metabolism of proteins: Mitochondrial protein degradation
Gene Ontology:
Molecular function: NAD+ kinase activity; protein homodimerization activity
Biological process: NAD+ metabolic process; NADP+ biosynthetic process
Cellular component: mitochondrion; mitochondrial matrix
Genetic constraint (gnomAD): Loss-of-function variants: 22 observed, 33.89 expected, observed/expected ratio (o/e) 0.65, 90% interval 0.46 to 0.93. The upper end of that interval is the gene's LOEUF score, 0.93, which puts it in group 3 of 6, group 1 being the genes least tolerant of losing a copy. Missense variants: 275 observed, 345.74 expected, observed/expected ratio (o/e) 0.8, 90% interval 0.72 to 0.88. Synonymous variants: 143 observed, 121.98 expected, observed/expected ratio (o/e) 1.17, 90% interval 1.02 to 1.35.
Gene-disease validity (ClinGen):
ClinGen rates the evidence that NADK2 causes each of these diseases.
progressive encephalopathy with leukodystrophy due to DECR deficiency (autosomal recessive): Moderate.
Homologues: Orthologues: chimpanzee NADK2 (99% identical), macaque NADK2 (99% identical), pig NADK2 (96% identical), mouse Nadk2 (92% identical), rat Nadk2 (92% identical), guinea pig NADK2 (87% identical), dog NADK2 (83% identical), tropical clawed frog nadk2 (68% identical), zebrafish nadk2 (66% identical), rabbit NADK2 (62% identical), Caenorhabditis elegans nadk-2 (42% identical), Caenorhabditis elegans nadk-1 (32% identical), and 1 more.
Diseases named in the same sentence as NADK2 in open-access papers:
NADK2 is named in the same sentence as 16 diseases in open-access papers, as found by Europe PMC text mining. Sharing a sentence is not in itself a finding about the gene and the disease. The quoted sentences say what the papers report.
epilepsy (2 papers, 2020 to 2024). A brain disorder characterized by episodes of abnormally increased neuronal discharge resulting in transient episodes of sensory or motor neurological dysfunction, or psychic dysfunction. "Recessive variants in NADK2 induce malformation of cortical development, ataxia, astatic myoclonic epilepsy, optic atrophy, and psychomotor retardation." (PMID 33426505, 2020).
Alzheimer disease (1 paper, 2025). A progressive, neurodegenerative disease characterized by loss of function and death of nerve cells in several areas of the brain leading to loss of cognitive function such as memory and language. "In T1DM, some of the terms annotated were related to myelin dysregulation (ARHGEF6, CNP, NADK2, PSAP, SLC25A12) and other neurological disorders, such as Alzheimer’s disease (i.e., POA2, APOC1, APOC3, CNP, GSK3B, PON1, PSAP, SELENBP1) or movement disorders." (PMID 39901093, 2025).
Delusion (1 paper, 2020). A delusion is a fixed false belief held despite evidence to the contrary. "Results revealed 32 genes for adolescent PENS, of which PAN3 mapped to adolescent cognitive disorganization and schizotypy in adulthood (perceptual aberrations), and NADK2 to adolescent negative symptoms and delusions of reference in UK Biobank; none overlapped with psychiatric disorders." (PMID 32152294, 2020).
hyperlysinemia (1 paper, 2020). Hyperlysinaemia is a lysine metabolism disorder characterized by elevated levels of lysine in the cerebrospinal fluid and blood. "On the other hand, one study suggested that the wide phenotype range of NADK2 deficiency due to NADK2 mutations might be the result of not only hyperlysinemia or DECRD, but could be also influenced by other NADPH-dependent processes." (PMID 32916978, 2020).
cancer (2 papers, 2021 to 2022). A tumor composed of atypical neoplastic, often pleomorphic cells that invade other tissues. "The minimally amplified region further includes NADK2 and MIR580, genes without a direct connection to cancer and therefore less likely drivers." (PMID 35706047, 2022).
NADK2 also shares sentences with these, for which no sentence is quoted: aortic stenosis (1 paper); Ataxia (1); Encephalopathy (1); Hepatic steatosis (1); Insulin resistance (1); microcephaly (1); movement disorder (1); neurological disorders (1); Obesity (1); optic atrophy (1); psychiatric disorder (1).